LEP (leptin)
Diseases named in the same sentence as LEP in open-access papers (continued):
Sharing a sentence is not in itself a finding about the gene and the disease.
periodontitis (48 papers, 2012 to 2025). An acute or chronic inflammatory process that affects the tissues that surround and support the teeth. "In the multiple LR model, leptin, adiponectin, and calprotectin levels were significantly associated with periodontitis (p < 0.001)." (PMID 41300847, 2025). "According to the results of the univariate LR analysis, high leptin and calprotectin levels and low adiponectin levels were significantly associated with periodontitis (p < 0.01)." (PMID 41300847, 2025). "Future studies involving patients with different stages of periodontitis are warranted to better elucidate the diagnostic and prognostic significance of salivary leptin, adiponectin, and calprotectin levels." (PMID 41300847, 2025). "Univariate LR analysis demonstrated that higher leptin and calprotectin levels were significantly associated with periodontitis." (PMID 41300847, 2025). "This chain of inflammatory reactions caused by elevated leptin levels further promotes periodontitis development." (PMID 38111655, 2023). "It has been reported that leptin and leptin receptor (LEPR) are expressed in healthy and inflamed gingival tissues, and elevated serum leptin concentration has been associated with increased chronic periodontitis." (PMID 35216099, 2022). "Although multiple studies have been conducted to find the association between periodontitis and serum levels of leptin and adiponectin, the findings were inconsistent." (PMID 28662701, 2017). "Although the association between periodontitis and serum levels of leptin and adiponectin has been studied extensively, the results were not consistent." (PMID 28662701, 2017). "In addition to its effects on bone tissue, leptin can also influence other periodontal tissues, exacerbating their destruction—a hallmark of periodontitis." (PMID 41154857, 2025). "Background/Objectives: This study aimed to evaluate salivary leptin, adiponectin, and calprotectin levels and to investigate the associations among these biomarkers in periodontally healthy individuals, as well as in patients with gingivitis and periodontitis." (PMID 41300847, 2025). "Therefore, the dual effects of leptin should be fully considered when treating periodontitis and associated diseases." (PMID 38111655, 2023). "Low serum leptin levels may thus be a risk factor for periodontitis, whereas low-dose exogenous leptin injections can reduce proinflammatory cytokine levels and promote bone formation." (PMID 38111655, 2023). "Interestingly, an association with higher systemic leptin levels in the presence of periodontitis and specifically in individuals with increased markers of periodontitis was observed in patients with early RA." (PMID 33499006, 2021). "Although leptin has a protective effect against periodontitis, the underlying mechanism remains unclear." (PMID 33967621, 2021). "Together, these studies indicate that leptin may be related to the development of chronic periodontitis; however, the underlying mechanism remains unclear." (PMID 33967621, 2021). "Therefore, the present systematic review and meta-analysis were performed to summarize individual study results into a quantitative estimation of the association between periodontitis and serum levels of leptin and adiponectin." (PMID 28662701, 2017). "Since periodontitis is caused by a complex bacterial biofilm, further studies should clarify whether leptin and its receptor are also regulated by other microorganisms, which are associated with periodontitis." (PMID 25136363, 2014). "Thereby, the PI3K-Akt signaling pathway, leptin-associated metabolic processes, and a proinflammatory profile of the immune system might predict patients with DS to develop an early on setting, severe aggressive periodontitis." (PMID 34545294, 2021).
periodontitis (continued). "The periodontitis group demonstrated significant bone loss, an increase in the number of inflammatory cells and vascular structures, an increase in resistin expression and synthesis, and a decrease in the expression of adiponectin, leptin, and its functional receptor." (PMID 32410876, 2020). "Furthermore, as a pleiotropic adipokine, leptin also exerted an effect on bone metabolism and might contribute to the alveolar bone destruction caused by periodontitis." (PMID 28662701, 2017). "According to the results of the ROC analysis, leptin, calprotectin, and adiponectin served as significant biomarkers for the diagnosis of periodontitis (p < 0.05)." (PMID 41300847, 2025). "Clinical studies further confirm that the severity of periodontitis in type 2 diabetes patients significantly correlates with the serum leptin/APN ratio, highlighting the critical role of adipokine balance in periodontitis development." (PMID 41246338, 2025). "Meta-analyses have confirmed a link between plasma leptin levels and periodontal diseases, with elevated serum leptin levels reported in patients with periodontitis." (PMID 41154857, 2025). "Leptin influences immune responses and inflammation, both of which contribute to the development of periodontitis and are closely interrelated processes." (PMID 41154857, 2025). "Two studies that investigated the relationship between salivary leptin levels and periodontal status reported that the levels were higher in patients with periodontitis than in healthy individuals." (PMID 41300847, 2025). "In cellular model studies, leptin has been shown to inhibit M2 macrophages and activate M1 macrophages, which contribute to the development of periodontitis by secreting large amounts of pro-inflammatory cytokines." (PMID 41154857, 2025). "Some studies have reported increased leptin levels in patients with periodontitis, while others have shown decreased levels." (PMID 41154857, 2025). "In this study, salivary leptin, adiponectin, and calprotectin levels were compared between periodontally healthy, gingivitis, and periodontitis groups." (PMID 41300847, 2025). "Clinical studies indicate that serum leptin levels in periodontitis patients positively correlate with inflammatory markers like IL-6 and TNF-α." (PMID 41246338, 2025). "According to the results of the ROC analysis, leptin, calprotectin, and adiponectin were identified as significant biomarkers for the diagnosis of periodontitis (p < 0.001)." (PMID 41300847, 2025). "Conversely, lower GCF levels of adiponectin and leptin have been observed in periodontitis patients, with an increase post-NSPT, suggesting a dynamic regulation of adipokines in response to periodontal inflammation and treatment." (PMID 40542868, 2025). "Periodontitis independently changes the serum levels of leptin, adiponectin, and C-reactive protein (CRP)." (PMID 40243433, 2025). "Receiver operating characteristic and logistic regression analyses identified salivary leptin, calprotectin, and adiponectin levels as significant biomarkers for distinguishing periodontal health, gingivitis, and periodontitis (p < 0.05)." (PMID 41300847, 2025). "Following 4 weeks of therapy, TNF-α correlations intensified markedly with leptin (ρ = 0.671, P < 0.01), resistin (ρ = 0.619, P < 0.01), and periodontal indices (gingival bleeding index: ρ = 0.245; periodontitis grading: ρ = 0.331; P < 0.01)." (PMID 41244040, 2025). "Salivary leptin levels were significantly decreased in the periodontally healthy group compared to the levels in both the gingivitis and periodontitis groups (p = 0.037 and p < 0.001, respectively; η2 = 0.110)." (PMID 41300847, 2025). "Nevertheless, the precise role of leptin in the development of periodontitis remains incompletely understood." (PMID 41154857, 2025).
periodontitis (continued). "In patients with periodontitis, alterations in the levels of various adipokines, such as adiponectin, leptin, visfatin, resistin and omentin-1, which condition periodontal healing and bone loss, have been studied." (PMID 38812668, 2024). "A recent meta‐analysis demonstrated elevated serum levels of leptin (pro‐inflammatory) and decreased serum levels of adiponectin (anti‐inflammatory) in periodontitis patients compared to controls within the total of study populations having a BMI <30 kg/m2." (PMID 39494478, 2024). "Periodontitis can upregulate serum leptin levels and, through the JAK2/STAT3 signaling pathway, regulate the involvement of the suppressor of cytokine signaling (SOCS) in cytokine signaling transduction inhibition, which affects T2D incidence." (PMID 38111655, 2023). "As abnormal expressions of adipokines such as visfatin, adiponectin and leptin have been found in the periodontal tissues of patients with periodontitis, the important role of adipokines in periodontitis has attracted more and more attention from researchers." (PMID 37231396, 2023). "In response to stimulation with periodontitis-derived virulence factors, specific adipokines, such as adiponectin, leptin, and resistin, are abnormally secreted and participate in IR through autocrine or paracrine mechanisms." (PMID 37321994, 2023). "Secondly, the gingiva mRNA expression of leptin, nampt/visfatin and resistin showed the maximum upregulation in the dual obese and periodontitis status, followed by in each single status, as compared with the control." (PMID 38069063, 2023). "This article reviews the existing literature and discusses leptin’s basic characteristics, its relationship with periodontitis, and its effects on periodontal tissue metabolism." (PMID 38111655, 2023). "In addition, triglycerides, total cholesterol, LDL-C, visfatin, resistin and leptin were significantly associated with periodontitis, indicating that these glycolipid metabolism mediators and these adipokines are crucial risk factors for the development of periodontitis." (PMID 37231396, 2023). "While the local leptin levels in periodontitis patients’ periodontal tissue decrease, there is an observed increase in serum leptin concentration." (PMID 38111655, 2023). "This implies that the substantial secretion of inflammatory factors in the mouths of periodontitis patients can potentially impact systemic circulation, thus heightening serum leptin levels, posing a threat to cardiovascular health." (PMID 38111655, 2023). "Oral microbial imbalance can influence both periodontitis and systemic health issues via the leptin pathway." (PMID 38111655, 2023). "Several studies have demonstrated a relationship between leptin and periodontitis, a local inflammatory disease that progressively weakens the supporting structures of the teeth, eventually leading to tooth loss." (PMID 38111655, 2023). "Serum leptin levels in patients with periodontitis were positively correlated with periodontal clinical parameters in various clinical trials." (PMID 38111655, 2023). "Elevated serum leptin levels can enhance the body’s inflammatory response and exacerbate periodontitis." (PMID 38111655, 2023). "Previously, the present author published a meta-analysis regarding the association between periodontitis and serum levels of leptin and adiponectin, finding that elevated serum leptin and decreased serum adiponectin were related to periodontitis." (PMID 37884949, 2023). "In other words, leptin, to a certain extent, acts as a bridge connecting local tissue inflammation in periodontitis and systemic diseases." (PMID 38111655, 2023). "Recent research has shown that leptin can promote the progression of periodontitis by inducing pro-inflammatory M1 macrophage skewing through the leptin/NLRP3 signaling pathway." (PMID 37798684, 2023). "Some studies have shown that that periodontitis can increase local periodontal leptin levels, which need to be further studied." (PMID 38111655, 2023).
periodontitis (continued). "More recently, a high serum concentration of leptin has been associated with generalized chronic periodontitis, with leptin being considered as a possible marker of inflammatory activity in chronic periodontitis." (PMID 35216099, 2022). "Of note, concentrations of leptin in the saliva and the gingival crevicular fluid of chronic periodontitis patients were significantly lower than those in healthy individuals 5,6." (PMID 33967621, 2021). "In summary, this study investigated the expression of leptin, OPG, and RANKL in the gingival tissue of patients with chronic periodontitis, as well as the regulatory effect of leptin on the expression of OPG and RANKL in human gingival fibroblasts." (PMID 33967621, 2021). "In the present study, leptin expression in the gingival tissue of the control group was significantly higher than that in the two chronic periodontitis groups." (PMID 33967621, 2021). "Patients with periodontitis have elevated serum levels of proinflammatory adipocytokines, such as leptin, visfatin, and resistin, and reduced serum levels of the anti‐inflammatory adipokine adiponectin." (PMID 34463983, 2021). "Regarding the other adipokines evaluated in the present study, leptin and its functional receptor were significantly downregulated in gingival tissues in periodontitis." (PMID 32410876, 2020). "Patients with chronic periodontitis also showed lower salivary leptin concentrations when compared to healthy volunteers." (PMID 30405010, 2018). "This study aimed to assess the difference in serum levels of leptin and adiponectin in patients with periodontitis and in periodontally healthy individuals and evaluate the changes in circulating leptin and adiponectin after periodontal therapy." (PMID 28662701, 2017). "Of the 25 included studies, all 16 studies focusing on the difference in serum levels of leptin and/or adiponectin between patients with periodontitis and healthy individuals employed the cross-sectional design." (PMID 28662701, 2017). "Our results provided evidence that circulating leptin is elevated and adiponectin is decreased in subjects with BMI < 30 and periodontitis." (PMID 28662701, 2017). "In conclusion, within the limitations of this study, the present meta-analysis supported elevated serum levels of leptin and decreased serum levels of adiponectin in patients with periodontitis compared with controls in the BMI <30 population." (PMID 28662701, 2017). "In this light, the subgroup analyses were performed based on BMI, which demonstrated a fluctuation in serum levels of leptin and adiponectin in patients with periodontitis having BMI <30 and ≥30." (PMID 28662701, 2017). "The present meta-analysis supported elevated serum levels of leptin and decreased serum levels of adiponectin in patients with periodontitis compared with controls in the BMI <30 population." (PMID 28662701, 2017). "The present study provided evidence that compared with healthy individuals, serum levels of leptin were elevated and those of adiponectin were decreased in patients with periodontitis having BMI <30." (PMID 28662701, 2017). "Significantly elevated serum levels of leptin and decreased serum levels of adiponectin in patients with periodontitis were observed in the subgroup analysis of body mass index (BMI) <30." (PMID 28662701, 2017). "Our findings suggested that leptin and adiponectin play as the potential biomarkers for periodontitis." (PMID 28662701, 2017). "By contrast, the leptin and adiponectin expressions were decreased in gingiva from periodontitis patients." (PMID 24707118, 2014). "A number of studies have shown that periodontitis results in elevated serum levels of leptin and that periodontal therapy can reduce serum leptin levels in periodontally-diseased patients." (PMID 25136363, 2014). "Further studies should clarify the regulation of leptin and its receptor in other periodontal cells and their contribution to the altered leptin levels in periodontitis." (PMID 25136363, 2014).
periodontitis (continued). "In contrast to NAMPT and resistin, leptin and adiponectin expressions were significantly reduced in gingiva from periodontitis patients." (PMID 24707118, 2014). "One study focused on leptin protein levels in gingiva from healthy sites and sites of gingivitis or periodontitis." (PMID 24707118, 2014). "On the contrary, leptin in gingival fluid shows decreased levels, especially in the presence of aggressive and advanced periodontitis, advising of a protective leptin role, although this topic is still disputed." (PMID 23009606, 2012). "The results of previous studies indicate that leptin may play a significant role in the development of periodontitis." (PMID 41154857, 2025). "Many studies support a pro-inflammatory role for leptin in the development of periodontitis." (PMID 41154857, 2025). "Furthermore, plasma leptin concentrations in periodontitis patients have been shown to correlate with pro-inflammatory cytokines implicated in disease pathogenesis, such as interleukin (IL)-1, IL-6, and tumour necrosis factor-alpha (TNF-α)." (PMID 41154857, 2025). "The mechanism by which leptin promotes periodontitis pathogenesis is still unknown; however, recent studies suggest that leptin induces proinflammatory M1 macrophage skewing and decreases M2 macrophage polarization." (PMID 40243433, 2025). "Our findings suggest that leptin may enhance the expression of cytokines involved in the progression of periodontitis." (PMID 41154857, 2025). "Leptin may contribute to the pathogenesis of periodontitis by modulating the expression of certain pro-inflammatory cytokines in periodontal ligament cells." (PMID 41154857, 2025). "Consistent with the increased inflammatory response observed in periodontal conditions, such as gingivitis and periodontitis, elevated levels of leptin and calprotectin, along with decreased levels of adiponectin, an anti-inflammatory adipokine, are anticipated." (PMID 41300847, 2025). "Elevated leptin levels, which have been observed in both migraine and periodontitis patients, may contribute to enhanced systemic inflammation and vascular dysregulation, providing a plausible mechanistic pathway." (PMID 40941475, 2025). "The results of this study suggest that leptin may contribute to the pathogenesis of periodontitis by modulating the expression of certain pro-inflammatory cytokines in periodontal ligament cells." (PMID 41154857, 2025). "There is a complex bidirectional relationship between serum leptin levels and periodontitis." (PMID 38111655, 2023). "Changes in serum and periodontal tissue’s leptin levels following nonsurgical periodontal treatment are critical for determining whether periodontitis and leptin have a bi-directional relationship." (PMID 38111655, 2023). "Despite accumulating evidence that leptin plays an important role in periodontal diseases, the mechanism by which it promotes periodontitis development is unknown." (PMID 36979821, 2023). "The inverse relationship observed between serum leptin levels and periodontitis in this study may be attributed to the specific sample selection and sample size." (PMID 38111655, 2023). "The enzyme-linked immunosorbent assay (ELISA) was used to detect the leptin levels in periodontitis patients’ (periodontitis patients without systemic diseases) gingival tissue, saliva, and gingival crevicular fluid (GCF)." (PMID 38111655, 2023). "In addition, some scholars have also found that leptin and resistin have a certain impact on the pathogenesis of periodontitis." (PMID 37231396, 2023). "High serum leptin levels in periodontitis suggest elevated severity of insulin resistance." (PMID 38111655, 2023).